EZH2 (enhancer of zeste 2 polycomb repressive complex 2 subunit)
Diseases named in the same sentence as EZH2 in open-access papers (continued):
Sharing a sentence is not in itself a finding about the gene and the disease.
cancer (continued). "Besides EZH2 overexpression, various point mutations in EZH2 have also been reported to result in high levels of H3K27me3 signals, including mutations at tyrosine 641 (Y641), alanine 677, and alanine 687 (A677 and A687), thereby inhibiting tumor suppressor genes to favor cancer progression." (PMID 35563864, 2022). "The functions of this co-repressor complex rely on expression of p65 and the methyltransferase activity of EZH2 for ERβ to elicit anti-cancer effects." (PMID 35177654, 2022). "EZH2 plays an important role in cancer development through transcriptional repression by chromatin remodeling." (PMID 35813302, 2022). "All in all, decreased EZH2 function diminishes anti-cancer CD8+ T cell responses, promoting immunological subverting." (PMID 36483029, 2022). "Given the evidence for EZH2 enzymatic gain-of-function being a cancer driver, the development of EZH2-specific inhibitors is an active and relevant area of investigation." (PMID 36430394, 2022). "Novel targets for cancer therapy have been identified and a methylase (KMT6A/EZH2), which produces the repressive H3K27me3 mark, and a demethylase (KDM1A/LSD1), which demethylates the active H3K4me2 mark, are now under clinical evaluation." (PMID 35406676, 2022). "Throughout this review article, we report that lncRNAs, circRNAs and miRNAs can regulate EZH2 expression in cancer cells." (PMID 35236381, 2022). "In human cancer cells, accumulation of EZH2 and H3K27me3 at the epigenetic regulatory element were diminished." (PMID 35729773, 2022). "Members of the PRC2 complex, including EZH2, are expressed in a subset of cancers, including bladder cancer." (PMID 36192513, 2022). "MEG3 exerted an anti‐cancer effect via stimulatory effects on EZH2 ubiquitination leading to its degradation." (PMID 35257481, 2022). "In multiple cancers, EZH2 is frequently over-activated to promote tumorigenesis, making it a promising drug target for cancer treatment." (PMID 36263173, 2022). "These new findings suggest that the HDAC2/EZH2/miR-148a/PDK1 axis is a novel mechanism for regulating cancer development and is a potentially promising target for therapeutic options in the future." (PMID 35892859, 2022). "It is reasonable to consider that EZH2 is the common cellular pathway involved in many disorders, including cancer, chronic pain, and negative emotions." (PMID 36467610, 2022). "EZH2 functions through the trimethylation of lysine in histone H3 and its aberrant expression has been heavily investigated in cancers." (PMID 35755302, 2022). "Most importantly, these compounds are still effective in cancer cells that have acquired resistance to EZH2 inhibitors." (PMID 36105358, 2022). "Most importantly, cancer cells are induced to a Synergistic effect by combinatory inhibition of NF-κB and EZH2." (PMID 36263173, 2022). "Since EZH2 plays distinct functions in different types of cancer and in metastases of different organs, targeting downstream effectors of EZH2, or EZH2’s enzyme function should be carefully evaluated." (PMID 35538070, 2022). "Huaier induces apoptosis and inhibits the proliferation of cancer cells by modulating the miR-26b-5p-EZH2 axis." (PMID 36248959, 2022). "Apart from functioning in cancer, EZH2 was also involved in several signalling pathway modulations, including playing a negative regulatory role in the process of muscle cell differentiation and the pathophysiologic processes of VC." (PMID 35784574, 2022). "First, reducing the expression of the EZH2 gene, which reduces cancer cell progression, invasion and metastasis trough EMT pathway, and second, by reducing miR-200c expression, which increases patients’ survival and response to chemo and radiotherapy." (PMID 36316365, 2022). "In according to critical role of EZH2 signaling in vital biological mechanisms and modulating cancer progression as well as affecting immune system, significant efforts have been made in developing novel EZH2 inhibitors." (PMID 35236381, 2022).
cancer (continued). "Results also showed that cancer cell proliferation was significantly attenuated when NF-κB and EZH2 inhibition were combined." (PMID 36263173, 2022). "With such a multitude of targets, it is hard to untangle each of the multiple roles of EZH2 in the cisplatin resistance of each cancer type." (PMID 36230683, 2022). "EZH2 is an essential therapeutic target of various cancers, and multiple inhibitors of EZH2 have entered clinical or preclinical studies." (PMID 36685834, 2022). "Elevated EZH2 has been observed in multiple solid tumor types, GC included; high level of EZH2 predicts poor outcome of cancer patients." (PMID 35802620, 2022). "With respect to the role of EZH2 in regulation of biological mechanisms, studies have focused on revealing its role in cancer." (PMID 35236381, 2022). "STAT3, which is closely related to cancer cell invasion and metastasis, was downregulated by EZH2 knockdown." (PMID 35208478, 2022). "It is considered that EZH2 has a master regulatory function in controlling several potent signaling pathways in cancer." (PMID 36230683, 2022). "Previous studies reported the correlation between EZH2 and miR-200 family in a few cancer types including hepatocellular, prostate, and OSCC malignancies." (PMID 36316365, 2022). "EZH2 is a critical epigenetic regulator involved in cell proliferation that is known to prevent cellular senescence in cancer cells via the inhibition of cyclin-dependent kinase inhibitors." (PMID 36009484, 2022). "Both increases and decreases in H3K27 methylation are found in cancer, and EZH2 can act as an activator of transcription independently of Polycomb." (PMID 35406676, 2022). "EREs have been reported in the EZH2 promoter, showing that E2 regulates the expression of the EZH2 gene in a couple of cancer cell types." (PMID 35197928, 2022). "Either overexpression of EZH2 or inactivation of negative regulators of PRC2 augments the dependency of cancer cells on H3K27me3 and PRC2, indicating that PRC2 inhibition can augment the therapeutic vulnerability of cancer cells." (PMID 35137163, 2022). "EZH2 frequently functions as a partner of YY1 in silencing miRNAs in various cancer models and the oncoprotein binding domain of YY1 is crucial for its interaction with EZH2." (PMID 36497298, 2022). "Our findings are consistent with previous studies indicating that EZH2 regulates gefitinib resistance in cancer cells." (PMID 36471952, 2022). "Experimental approaches such as RNA-based silencing (siRNAs and shRNAs) have also been widely used to modulate EZH2 signaling in cancer research." (PMID 36230683, 2022). "EZH2 is an epigenetic regulator with an increased expression and activity in many cancer types, which, in general, potentiates cancer growth and expansion." (PMID 36230683, 2022). "EZH2 plays a significant role in autophagy, apoptosis, DNA repair and cellular senescence inhibition, conferring itself an important role in cancer initiation, progression and metastasis." (PMID 35326637, 2022). "Overall, experiments agree with the fact that lncRNAs can induce cancer progression via inducing EZH2 expression." (PMID 35236381, 2022). "Qiu C. and colleagues reported that lncPVT1 is able to enhance cancer progression by targeting miR-526b leading to the upregulation of its target EZH2 (Enhancer of zeste homolog 2) which stimulates proliferation, where it is also a prognostic marker." (PMID 35090471, 2022). "Previously, we have shown the classical gene silencing function of EZH2 where death receptors are epigenetically suppressed in cancer stem cells." (PMID 36446780, 2022). "Generally, the increased activity of EZH2 potentiates cancer cell proliferation, survival, migration, invasion, and epithelial-to-mesenchymal transition (EMT)." (PMID 36230683, 2022). "The present review provides a comprehensive discussion of EZH2 signaling role in cancer, and its regulation by upstream mediators, such as ncRNAs." (PMID 35236381, 2022).
cancer (continued). "In contrast to the unequivocal roles of EZH2 in cancer development, understanding of the function of EZH2 in the female reproductive tract is far from complete." (PMID 36555314, 2022). "In line with that, overlapping, but also diverse, roles of EZH2 were described in prostate, breast, ovarian, lung, bladder, and many other cancer types." (PMID 36230683, 2022). "Accumulating evidence demonstrates that EZH2 as the catalytic subunit of PRC2 also directly or indirectly plays a key role in the metabolic process of cancer cells." (PMID 36195655, 2022). "MiRNAs can dually induce/inhibit EZH2 in cancer cells to affect downstream targets such as Wnt, STAT3 and EMT." (PMID 35236381, 2022). "Enhancer of zeste homology 2 (EZH2) has obtained increasing attention in recent years in the field of cancer therapy." (PMID 36292072, 2022). "EZH2 was found downregulated in response to short-chain fatty acids produced by periodontal pathogens, which contributes to cancer development." (PMID 35132337, 2022). "It is noteworthy that there are studies demonstrating that EZH2 can regulate miRNAs and result in cancer progression." (PMID 35236381, 2022). "Nevertheless, PRC2-independent functions of EZH2, e.g., the modification of protein activity by methylation or direct binding, have also been described in different cancer entities." (PMID 35740494, 2022). "Particularly, various reports have focused on the link between the enhancer of zeste homolog 2 (EZH2) and cancer." (PMID 36430394, 2022). "EZH2 can combine with the CDH1 (encoding E-cadherin) promoter to decrease the expression of E-cadherin and promote the metastasis and invasion of cancer cells." (PMID 35505294, 2022). "In the present study, we first analyzed EZH2 expression and its prognostic value in a series of TCGA clinical samples of human cancers." (PMID 35627262, 2022). "In a recent work on A549 cell model, the authors showed that EZH2 knockdown enhanced the sensitivity of cancer cells to cisplatin by inhibiting viability and promoting apoptosis." (PMID 36230683, 2022). "EZH2 also contributes to drug resistance in various types of cancer through transcriptional regulation." (PMID 36086687, 2022). "The fact that EZH2 activity is frequently upregulated in different cancer types imposes EZH2 as an appealing anticancer drug target." (PMID 36230683, 2022). "Previous studies have confirmed that multiple EZH2 targets in cancers belong to the cell cycle protein dependent kinase inhibitor (CKI) family, which negatively regulates the cell cycle." (PMID 36313363, 2022). "EZH2 is a well-known oncogene and has been commonly recognized as a biomarker for many types of cancers." (PMID 35184652, 2022). "As an epigenetic regulator, enhancer of zeste homology (EZH2) inhibits gene transcription by trimethylation of histone H3K27 in cancer cells." (PMID 35935878, 2022). "EZH2, a histone methyltransferase, is commonly overexpressed in most cancers and correlates with poor prognosis." (PMID 36009484, 2022). "As EZH2 has been described as major epigenetic regulator involved in tumorigenesis of several cancers, we further focused on its regulation by IGF2BP1." (PMID 35565249, 2022). "Several studies have shown the elevated expression level and cancer promotion effect of EZH2 in HCC, mainly through the polycomb repressive complex 2 (PRC2)-dependent roles as transcriptional repressors." (PMID 36578923, 2022). "Cumulative evidences shows that EZH2 is overexpress in many cancer types including breast cancer, esophageal cancer, and GC." (PMID 36401232, 2022). "E2F, in turn, is able to enhance EZH2 transcription in different human cancers by directly binding to the EZH2 promoter which facilitates cell cycle entry and S phase progression." (PMID 35565249, 2022). "To date, few experiments have investigated the role of shRNAs in EZH2 silencing and suppressing cancer progression." (PMID 35236381, 2022).
cancer (continued). "More and more evidence has suggested that LncRNAs acted as a crucial role in EZH2-mediated epigenetic regulation in multiple cancer types." (PMID 35802620, 2022). "Multiple studies have shown a correlation between high EZH2 expression and poor prognosis in different cancers, including HCC." (PMID 36071871, 2022). "Mounting evidence has suggested that EZH2 participated in the alteration of metabolic profiles in cancer through diverse pathways, covering glucose, lipid, amino acid metabolism." (PMID 35935878, 2022). "Anticancer therapies targeting HDACs and EZH2 within epigenetic regulatory complexes have been individually effective at treating various cancer types and have received Food and Drug Administration (FDA) approval." (PMID 35795673, 2022). "EZH2 is an epigenetic regulator of cell proliferation that is overexpressed in most cancers, and high levels of EZH2 expression correlate with poor prognosis." (PMID 36009484, 2022). "Overall, these studies agree with the regulatory role of EZH2/EMT axis by lncRNAs in different cancers." (PMID 35236381, 2022). "The vital role of EZH2 in tumorigenesis highlight targeting EZH2 as a promising therapeutic strategy in cancer treatment." (PMID 35449124, 2022). "To make a comparison between HepG2 and THLE-2 cells, we found specifically bound genes by EZH2 in HepG2 cells (1,965 genes) were significantly enriched in cancer related pathways, including those in cancer." (PMID 36578923, 2022). "Similar findings correlating high levels of EZH2 with aggressiveness and advanced disease have emerged in other human cancers." (PMID 35563864, 2022). "EZH2 has been found to be upregulated in a variety of cancers, including colorectal, prostate, and breast cancer." (PMID 36619866, 2022). "Multiple kinds of EZH2 inhibitor have been developed, and several clinical trials of target EZH2 for different cancer types are ongoing." (PMID 35449124, 2022). "DZNep was previously shown to invoke depletion of H3K27 trimethylation in cancer cells, suggesting inhibitory activity on the MTase EZH2, the enzymatic component of the PRC2 complex." (PMID 35833542, 2022). "It is known that EZH2 has become a target for inhibition as it was upregulated in a variety of cancers." (PMID 35743172, 2022). "Epigenetic regulation is adopted as a new method for cancer treatment, among which the inhibition of EZH2 can provide targeted epigenetic regulation." (PMID 36195655, 2022). "The pairwise boxplot of 52 pairs of PRAD tissues and matched adjacent normal tissues revealed that most of the cancer tissues showed a higher level of EZH2 (p-value < 0.001)." (PMID 36358967, 2022). "The relation of the abnormal expression of EZH2 with poor prognosis has been demonstrated in a variety of malignant tumors." (PMID 36195655, 2022). "To test the direct regulatory link, we knocked down HDAC2 and EZH2 expression using siRNAs in the cancer cell lines, and found that EZH2 and HDAC2 silencing in the cells significantly decreased PDK1 expression." (PMID 35892859, 2022). "The clinical aspect of EZH2 inhibitors is also attributed to improving ability of oncologists in suppressing metastasis and angiogenesis in cancer." (PMID 35236381, 2022). "The EZH2 small-molecule inhibitor is being evaluated in clinical trials for the treatment of cancers, including tazemetostat, thus we further evaluated the relevance of DMDRMR/miR-378a-5p axis in the efficacy of tazemetostat." (PMID 35562342, 2022). "EZH2 is capable of affecting the occurrence and progression of human cancers by modulation of cell biological processes." (PMID 35322532, 2022).
cancer (continued). "EZH2 also has been shown to regulate inflammatory cytokines and chemokines in several different cell types including cancer cells, CD4+ T cells, regulatory T cells, Kupffer cells, and macrophages." (PMID 36038549, 2022). "Enhancer of Zeste Homolog 2 (EZH2) has attracted increasing interest in recent years, and specific molecular inhibitors are currently being tested in various cancer entities." (PMID 35740494, 2022). "Further investigating the mechanisms whereby EZH2 promotes cancer is therefore of great significance." (PMID 35013218, 2022). "The downregulated EZH2 transcriptional targets were enriched in response to the hormone GO term and pathways in cancer." (PMID 35846880, 2022). "PRCs often play important roles in disease pathogenesis, and the catalytic subunit of PRC2, EZH2 (Enhancer of Zeste Homolog 2), is overexpressed in several cancers." (PMID 35326450, 2022). "Similar to the initial studies on the effects of miR-101a on human EZH2 in cancer cells, over-expression of miR-101a-3p suppresses Ezh2 protein levels in mouse MC3T3 osteoblasts cells maintained in either basal or osteogenic medium." (PMID 35922466, 2022). "EZH2 induces cancer cell proliferation and osteoclast maturation, whereas EZH2 knockdown decreases bone metastasis incidence and outgrowth in vivo." (PMID 35538070, 2022). "In this section, we discuss the role of siRNAs and delivery systems to silence EZH2 and suppress cancer malignancy." (PMID 35236381, 2022). "In line with our findings, numerous studies have confirmed upregulated expression of EZH2 in cancers." (PMID 35668081, 2022). "In recent years, one marker that has attracted increasing interest in various cancer entities is Enhancer of Zeste Homolog 2 (EZH2)." (PMID 35740494, 2022). "Numerous documents have demonstrated the crucial role of EZH2 in cancer initiation, progression, metastasis, and drug resistance." (PMID 34923811, 2022). "Although its expression was decreased in OV compared to normal tissue, higher EZH2 expression induced peritoneal metastasis, such as cancer stem cells." (PMID 35723302, 2022). "SUV39H1 and EZH2 has emerged as a drug target and results from studies conducted on SUV39H1 and EZH2 have helped in the development of several potential therapeutic strategies that can be followed to treat cancer." (PMID 36028818, 2022). "Cancer cells that express EZH2 have reduced CXCR9 expression and decreased effector T-cell infiltration of tumors." (PMID 35795673, 2022). "EZH2 genomic amplification and overexpression occur across many types of cancers, including AML, and enhance tumorigenesis." (PMID 36232694, 2022). "Studies have found that EZH2 has high expression activity in a variety of cancer diseases with high incidence, such as breast cancer, stomach cancer, bladder cancer, and prostate cancer." (PMID 35321452, 2022). "In the next sections, we will provide a summary of miRNA and EZH2 interaction in different cancers and how this interaction can affect the malignancy of cancer cells." (PMID 35236381, 2022). "Collectively, these results demonstrate that both Dicer‐mediated sorafenib sensitization and cancer stemness suppression are regulated by EZH2." (PMID 35253323, 2022). "Malignant cells inhibit T cell EZH2 activity by limiting aerobic glycolysis, reducing T cell-mediated anti-cancer immunity." (PMID 36483029, 2022). "A mechanism has been described in which EZH2 expression-mediated downregulation of DNA damage repair leads to accumulation of recurrent RAF1 gene amplification in Cancer Initiated Cells (CIC), which activates p-ERK-β-catenin signaling and enhanced CIC growth." (PMID 35955891, 2022). "In the present review, our aim is to focus on a special signaling pathway known as enhancer of zeste homolog 2 (EZH2) in cancer, and its regulation by major upstream mediators, called non-coding RNAs (ncRNAs)." (PMID 35236381, 2022).